ANKRD11 (ankyrin repeat domain 11)
Description:
Chromatin regulator which modulates histone acetylation and gene expression in neural precursor cells (By similarity). May recruit histone deacetylases (HDACs) to the p160 coactivators/nuclear receptor complex to inhibit ligand-dependent transactivation. Has a role in proliferation and development of cortical neural precursors. May also regulate bone homeostasis (By similarity).
Synonyms: ANCO1; LZ16; T13; ANCO-1
Tractability: PROTAC: ubiquitination databases record sites on it.
Gene: Protein-coding gene on chromosome 16 (89,267,619 to 89,490,561, reverse strand). Ensembl gene ENSG00000167522.
Subcellular location: Nucleus
Subcellular location (Human Protein Atlas): Nucleoplasm; Cytosol
Gene Ontology:
Biological process: face morphogenesis; odontogenesis of dentin-containing tooth; skeletal system morphogenesis; face development; head morphogenesis
Cellular component: cytosol; nucleoplasm; nucleus
Genetic constraint (gnomAD): Loss-of-function variants: 17 observed, 193.65 expected, observed/expected ratio (o/e) 0.0878, 90% interval 0.059 to 0.13. The synonymous counts are far from expectation, so gnomAD's model fits this gene poorly and the ratio says little. Missense variants: 3,655 observed, 3,484.2 expected, observed/expected ratio (o/e) 1.05, 90% interval 1.02 to 1.08. Synonymous variants: 1,901 observed, 1,498.4 expected, observed/expected ratio (o/e) 1.27, 90% interval 1.22 to 1.32.
Gene-disease validity (ClinGen):
ClinGen rates the evidence that ANKRD11 causes each of these diseases.
KBG syndrome (autosomal dominant): Definitive. KBG syndrome is a rare condition characterized by a typical facial dysmorphism, macrodontia of the upper central incisors, skeletal (mainly costovertebral) anomalies and developmental delay.
Homologues: Orthologues: chimpanzee ANKRD11 (94% identical), macaque ANKRD11 (94% identical), dog ANKRD11 (79% identical), guinea pig ANKRD11 (79% identical), rat Ankrd11 (79% identical), mouse Ankrd11 (79% identical), pig ANKRD11 (72% identical), tropical clawed frog ankrd11 (59% identical), zebrafish ankrd11 (52% identical).
Diseases named in the same sentence as ANKRD11 in open-access papers:
ANKRD11 is named in the same sentence as 83 diseases in open-access papers, as found by Europe PMC text mining. Sharing a sentence is not in itself a finding about the gene and the disease. The quoted sentences say what the papers report.
KBG syndrome (71 papers, 2014 to 2025). "This prompted exome sequencing, which identified a pathogenic mutation in the ANKRD11 gene, diagnostic of KBG syndrome." (PMID 40760574, 2025). "Heterozygous LOF variants in ANKRD11 are, most commonly, associated with KBG syndrome, but a phenotypic overlap with CdLS has been recurrently reported." (PMID 40677927, 2025). "Collectively, we concluded that the microdeletion spanning the upstream region and 5′UTR of ANKRD11 causes KBG syndrome." (PMID 40004465, 2025). "KBG syndrome, first described in 1975, is caused by loss of function heterozygous mutation or deletion of ANKRD11." (PMID 40760574, 2025). "Exome sequencing revealed a pathogenic mutation in ANKRD11 (ankyrin repeat domain 11), diagnostic of KBG syndrome." (PMID 40760574, 2025). "KBG syndrome (MIM 148050) is a neurodevelopmental disorder caused by deletion (22% of cases) or sequence variants (78% of cases) of the ANKRD11 gene." (PMID 40760574, 2025). "Loss-of-function mutations in ANKRD11 have been associated with a wide spectrum of clinical phenotypes, including KBG syndrome, as well as other presentations such as Coffin–Siris-like syndrome and intellectual disabilities with infantile spasms." (PMID 40004465, 2025). "In conclusion, this case report highlights the complexities of diagnosing rare genetic syndromes, such as KBG syndrome, associated with the ANKRD11 gene abnormality." (PMID 40760574, 2025). "Heterozygous chromosomal deletion encompassing the partial or entire ANKRD11 gene, as well as the loss of function mutations, result in haploinsufficiency of the gene, leading to KBG syndrome." (PMID 40004465, 2025). "Haploinsufficiency of another epigenetic regulator, ANKRD11, is recognized as the primary genetic cause of KBG syndrome, suggesting a functional interplay between ANKRD11 and SETD5." (PMID 41283518, 2025). "A pathogenic mutation was identified in ANKRD11, diagnostic of KBG syndrome (ANKRD11 c.3770_3771delAA) (p.K1257Rfs*25)." (PMID 40760574, 2025). "ANKRD11 (Ankyrin Repeat Domain 11) is a chromatin regulator and a causative gene for KBG syndrome, a rare developmental disorder characterized by multiple organ abnormalities, including cardiac defects." (PMID 38951500, 2024). "Our review offers crucial insights into the association between ANKRD11 variants and short stature and provides valuable guidance for precise clinical diagnosis and treatment of patients with KBG syndrome." (PMID 39135054, 2024). "ANKRD11 (ankyrin repeat domain 11) is a chromatin regulator and the only gene associated with KBG syndrome, a rare neurodevelopmental disorder." (PMID 38616269, 2024). "This novel association broadens the neuroradiological spectrum of KBG syndrome, and further prompts to investigate the potential functions of ANKRD11 in cerebellar development." (PMID 38334877, 2024). "Inherited or de novo mutations in or deletions of ANKRD11 are associated with KBG syndrome (OMIM #148050; named after the initials of the first three patients)." (PMID 38616269, 2024). "KBG syndrome is caused by single nucleotide pathogenic variants and small indels in ANKRD11 or lager copy number variants (mostly deletions) at 16q24.3 involving ANKRD11." (PMID 39346806, 2024). "Since the identification of variants in the gene (ANKRD11) responsible for KBG syndrome, wider phenotypes are emerging." (PMID 38317675, 2024). "Together, our results identify a new role for Ankrd11 in OB development and a novel OB-related clinical phenotype linked to KBG syndrome." (PMID 38616269, 2024). "Whole exome sequencing identified a novel frameshift variant in the ANKRD11 gene which ultimately led to the diagnosis of KBG syndrome." (PMID 39831200, 2024). "Loss of function variants (both frameshift and nonsense, mainly involving exon 9) is the most frequent (69%) cause of KBG syndrome, being ANKRD11 a dosage-sensitive gene." (PMID 38334877, 2024).
KBG syndrome (continued). "Two unrelated individuals with uDEEs were positive for the KBG syndrome episignature (KBGS_MRD23) caused by pathogenic variants in ANKRD11." (PMID 39107278, 2024). "Ankrd11 is a chromatin regulator that is strongly associated with KBG syndrome, a rare disorder that includes heart defects." (PMID 38951500, 2024). "The ANKRD11 gene, initially associated with KBG syndrome (OMIM: 148050), has also been linked to CdLS due to the remarkable phenotypic overlap between the two syndromes." (PMID 38673696, 2024). "KBG syndrome is genetically determined by heterozygous pathogenic variants in ANKRD11 (ankyrin repeat domain-containing protein 11), a member of the family of ankyrin repeat-containing cofactors." (PMID 38334877, 2024). "Heterozygous pathogenic variants in ANKRD11 or 16q24.3 microdeletions containing ANKRD11 cause KBG syndrome (OMIM #148050), an autosomal dominant multisystem developmental disorder." (PMID 38951500, 2024). "After review of the literature, this unusual presentation expands the phenotypic spectrum of KBG syndrome and adds ANKRD11 variants to the list of genetic alterations associated with tremor-dominant movement disorders." (PMID 39346806, 2024). "In this study we have identified a previously unreported frameshift variant (NM_013275.6:c.2589dup) in ANKRD11 that causes KBG syndrome." (PMID 39831200, 2024). "KBG syndrome (OMIM #148050) is a rare genetic disease caused by ANKRD11 gene mutation or deletion of 16q24.3, including ANKRD11, and is characterized by neurodevelopmental disorders, macrodontia, and craniofacial dysmorphism." (PMID 36564961, 2023). "Patient #77 carried a mutation in the ANKRD11 gene, which encodes an ankyrin repeat domain-containing protein, corresponding to the phenotype of KBG syndrome (OMIM#148,050) with an autosomal dominant inheritance pattern." (PMID 37605180, 2023). "KBG syndrome is caused by heterozygous mutations of the Ankyrin repeat domain 11 (ANKRD11) gene or deletions of the chromosome 16q24.3 region including ANKRD11." (PMID 36564961, 2023). "Genetic variants in Ankyrin Repeat Domain 11 (ANKRD11) and deletions in 16q24.3 are known to cause KBG syndrome." (PMID 35970914, 2022). "Mutations in ANKRD11 (ankyrin repeat domain 11) are reported to be associated with KBG syndrome and intellectual disability." (PMID 36357925, 2022). "KBG syndrome is caused by a heterozygous variant or 16q24.3 microdeletions of the ANKRD11 gene (OMIM #611192), thereby altering its function." (PMID 36012925, 2022). "We will also address KBG syndrome, which was thought to be caused specifically by ANKRD11 (ankyrin repeat domain containing 11) gene mutations, but for which a role for SETD5 was recently suggested." (PMID 36685966, 2022). "Most patients with KBG syndrome possess a pathogenic variant involving the ANKRD11 (ankyrin repeat domain-containing protein 11) gene, which was reported as a causative gene in 2011." (PMID 34440431, 2021). "KBG syndrome (KBGS) (MIM #148050) is a rare Mendelian condition caused by heterozygous mutations in ANKRD11 or microdeletions encompassing the gene." (PMID 33917340, 2021). "The gold standard for diagnosis of KBG syndrome is genetic testing to detect ANKRD11 variants or 16q24.3 deletion involving the gene." (PMID 33996804, 2021). "The genetic causes of KBG syndrome include single nucleotide variants and small indels of ANKRD11 or microdeletions of 16q24.3 involving ANKRD11, accounting for approximately 83% and 17% of cases, respectively." (PMID 33653342, 2021). "We found a de novo variant in ANKRD11 [p.(Ala2265fs)] which is in agreement with her phenotype and KBG-syndrome (#148050; KBGS)." (PMID 33710394, 2021). "Craniofacial and palate anomalies associated with KBG syndrome patients suggest a direct role for ANKRD11 during craniofacial development." (PMID 33996804, 2021).
KBG syndrome (continued). "In this study, we report the analysis of a de novo heterozygous frameshift ANKRD11 variant in a Chinese girl with KBG syndrome and the corresponding phenotypes." (PMID 33653342, 2021). "In the group of nine patients with wide and delayed closure of anterior fontanels and mutations in the ANKRD11 gene, 7/9 patients (78%) had a suspicion of KBG syndrome." (PMID 34440431, 2021). "The Ankrd11 locus is associated with KBG syndrome in humans, which presents with generally delayed bone mineralization as well as craniofacial characteristics including palate abnormalities." (PMID 34779766, 2021). "KBG syndrome (KBGS) is a rare Mendelian condition caused by heterozygous mutations in ANKRD11 or microdeletions in chromosome 16q24.3 encompassing the gene." (PMID 33917340, 2021). "Most patients with KBG syndrome are found to have a mutation in the ANKRD11 gene or a chromosomal rearrangement involving this gene." (PMID 34440431, 2021). "Last, the ANKRD11 gene should be counted, as it was firstly associated with KBG syndrome and then associated with CdLS." (PMID 34356091, 2021). "To date, more than 300 variants in ANKRD11 have been identified in cases of KBG syndrome according to ClinVar database, and the majority of these variants occurred de novo." (PMID 33653342, 2021). "ANKRD11 gene variants, or microdeletions of the 16q24.3 chromosomal region encompassing the ANKRD11 gene, cause KBG syndrome, a rare autosomal dominant congenital disorder with variable neurodevelopmental and craniofacial involvement." (PMID 33996804, 2021). "ANKRD11 deletions are frequently described in association with KBG syndrome, the duplications being less frequent (one case described before)." (PMID 32760686, 2020). "Seven individuals with prominent extracardiac anomalies and developmental delay had disease-causing de novo variants, such as p.(Pro1747Argfs*49) in ANKRD11 (KBG syndrome), or p.(Arg5225Cys) in KMT2D (Kabuki syndrome)." (PMID 32037394, 2020). "Heterozygous mutations in ANKRD11 lead to KBG syndrome, which is characterized by macrodontia of the upper central incisors, distinctive craniofacial findings, short stature, skeletal anomalies and neurologic symptoms including ID/DD and seizures." (PMID 31088393, 2019). "KBG syndrome is caused by ankyrin repeat domain-containing protein 11 (ANKRD11) gene haploinsufficiency, resulting from either loss-of-function intragenic mutations or 16q24.3 chromosome microdeletions in encompassing the gene." (PMID 31703437, 2019). "Our data expand the allelic spectrum of ANKRD11 mutations, providing the first Brazilian case of KBG syndrome." (PMID 30642272, 2019). "KBG syndrome is a rare multisystem developmental disorder caused by ankyrin repeat domain-containing protein 11 (ANKRD11) gene haploinsufficiency, resulting from either intragenic loss-of-function mutations or microdeletions encompassing the gene." (PMID 31703437, 2019). "Intragenic variants and microdeletions including ANKRD11 have been reported to result in KBG syndrome." (PMID 29258554, 2017). "The Ankrd11Yod/+ or Yoda mouse was reported before the identification of ANKRD11 mutations in KBG syndrome." (PMID 29258554, 2017). "Seventy-nine of the 86 previously reported ANKRD11 variants in patients with KBG syndrome are truncating and the majority of these cluster to the ninth exon (NM_013275.5), with only a handful of recurrent mutations being reported to date." (PMID 29258554, 2017). "We established single gene analysis of ANKRD11 (TS) as a diagnostic test at Bristol Genetics Laboratory in 2014 for patients considered to have KBG syndrome." (PMID 27667800, 2016). "This single-nucleotide duplication is predicted to lead to a premature stop codon and loss of function in ANKRD11, thereby implicating it as contributing to the proband's symptoms and yielding a molecular diagnosis of KBG syndrome." (PMID 27900361, 2016).
KBG syndrome (continued). "ANKRD11 regulates chromatin modification and has been found to be associated with autism and KBG syndrome (rare disorder marked by dental, neurobehavioral, craniofacial and skeletal anomalies)." (PMID 27903268, 2016). "KBG syndrome is characterized by short stature, distinctive facial features, and developmental/cognitive delay and is caused by mutations in ANKRD11, one of the ankyrin repeat‐containing cofactors." (PMID 27667800, 2016). "We report the identification of a de novo mutation in ANKRD11, which led to the recognition of KBG syndrome in the sequenced proband." (PMID 27900361, 2016). "Three de novo mutations were identified in ANKRD11 demonstrating a phenotypic overlap with KBG syndrome." (PMID 25125236, 2014). "For instance, in the ANKRD11 gene we identified the p.(Arg2536Trp) variant which is situated within a predicted highly charged alpha-helix region where other ANKRD11 pathogenic variants have been observed in individuals with KBG syndrome (OMIM#148,050)." (PMID 40019509, 2025). "The genesis of KBG syndrome (OMIM 148050) involves either heterozygous mutations within the ankyrin repeat domain-containing protein 11 (ANKRD11) or the deletions in the 16q24.3 region that include the ANKRD11 gene." (PMID 40574944, 2025). "A study conducted in 2020 involving 13 Chinese patients with KBG syndrome revealed that truncating variants in the ANKRD11 gene were more likely to be associated with global growth retardation and intellectual disability/learning difficulties compared to missense variants in the same gene." (PMID 39831200, 2024). "Moreover, our study highlights a novel clinical sign of KBG syndrome linked to ANKRD11 perturbations in mice and humans." (PMID 38616269, 2024). "Consequently, we propose ANKRD11-KBG syndrome to be included in the list of monogenic causes of a combined tremor syndrome." (PMID 39346806, 2024). "Notably, there is no record of the ANKRD11 (NM_013275.5:c.2589dup) frameshift variant among the identified variants of the ANKRD11 gene associated with KBG syndrome in the NCBI database to date." (PMID 39831200, 2024). "However, KBG syndrome, a genetic condition caused by mutations in the ANKRD11 gene, was also considered in the differential diagnosis due to its similarities with CdLS." (PMID 39703245, 2024). "KBG syndrome is a monogenic disorder caused by heterozygous pathogenic variants in ANKRD11." (PMID 39346806, 2024). "Among those, five de novo pathogenic variants were identified in ANKRD11, causing KBG syndrome, characterized by macrodontia of the upper central incisors, characteristic facial features, short stature, developmental delay/intellectual disability, and behavioral issues." (PMID 36980980, 2023). "KBG syndrome is a rare genetic disorder involving macrodontia of the upper central incisors, craniofacial, skeletal, and neurologic symptoms, caused either by a heterozygous variant in ANKRD11 or deletion of 16q24.3, including ANKRD11." (PMID 36564961, 2023). "KBG syndrome is an autosomal dominant disorder caused by pathogenic variants in the ankyrin repeat domain‐containing protein 11 gene (ANKRD11) or chromosomal microdeletions in 16q24.3 including ANKRD11." (PMID 37501353, 2023). "ANKRD11 is the only known causative gene of KBG syndrome, which is characterized by macrodontia, craniofacial findings, short stature, multiple skeletal anomalies including vertebrae and limbs, neurologic involvement including global developmental delay, seizures, and intellectual disability." (PMID 35360850, 2022). "Overall, the extent and variety of reported deficiencies in KBG syndrome patients could be attributed to the role of ANKRD11 as a chromatin regulator." (PMID 35970914, 2022). "The proliferation of cultured cortical precursor cells from Yoda mice, which harbor a missense mutation of Ankrd11 similar to a mutation identified in a KBG syndrome patient, was found to be impaired, and the defect was rescued by ectopic overexpression of HDAC3." (PMID 36685966, 2022).